MIR920 (microRNA 920)
Synonyms: hsa-mir-920; MIRN920
Gene: MicroRNA gene on chromosome 12 (24,212,421 to 24,212,495, forward strand). Ensembl gene ENSG00000216192.
Gene Ontology:
Biological process: miRNA-mediated post-transcriptional gene silencing
Cellular component: RISC complex